CLU (clusterin)
Diseases named in the same sentence as CLU in open-access papers (continued):
Sharing a sentence is not in itself a finding about the gene and the disease.
ovarian carcinoma (continued). "It is reported that aberrantly excreted urinary O-glycosylated proteins (clusterin, leucine-rich alpha-2-glycoprotein, and kininogen) could serve as potential biomarkers for the early detection of early stage ovarian cancer." (PMID 28401167, 2017). "Further glycopeptide analysis identified unusual N- and O-glycans in clusterin, fibulin and hemopexin glycopeptides, which may be important in metastasis of ovarian cancer." (PMID 28894650, 2017). "The expression of clusterin is significantly correlated with the biological characteristics of ovarian cancer cells, it may be a potential molecular for ovarian cancer treatment." (PMID 26293319, 2015). "Similarly, clusterin expression is associated with FIGO stage and histological type in ovarian cancer." (PMID 26293319, 2015). "Moreover, we assessed the proliferation, migration, invasion, clonability, cell cycle of ovarian carcinoma cells after clusterin gene silencing." (PMID 26293319, 2015). "The level of clusterin expression maybe is an important prognostic factor in the assessment of the aggressive nature of ovarian cancer." (PMID 26293319, 2015). "Alternatively, overexpression of CLU might increase migration and invasion capacity of ovarian cancer cells." (PMID 22185350, 2011). "Moreover, our study showed that s-CLU is well expressed in many ovarian cancer cell lines assayed and resistant ovarian cancer tissues." (PMID 22185350, 2011). "We conclude that CLU could be a potential molecular marker to predict chemoresistance in patients with ovarian cancer." (PMID 22185350, 2011). "In the current study, we firstly demonstrated that OGX-011, a second-generation antisense oligodeoxynuclotide targeting the translation initiation site of human CLU gene exon II with a long tissue half-life, can modulate sensitivity to TX in an acquired TX-resistant ovarian cancer cell line." (PMID 22185350, 2011). "However, prognostic significance of CLU expression remains controversial for ovarian cancer patients." (PMID 22185350, 2011). "We conclude that CLU could be a potential molecular target to predict survival while targeting this s-CLU may improve survival of patients with ovarian cancer." (PMID 22185350, 2011). "Importantly, CLU-shRNA significantly reduced the generation of TX-resistant clones if compared with mock transfectants indicating that s-CLU expression is necessary for ovarian cancer cells to develop TX resistance probably to inhibit cell growth." (PMID 22185350, 2011). "Thus, prognostic significance of CLU expression in ovarian cancer patients remains controversial." (PMID 22185350, 2011). "We also found that apoptosis-related genes, URI1, PAK2, PARP1, CLU and TIMP3, were highly expressed, while immune-related genes, UBB, RPL11, CAV1, NUPR1 and Hsp90ab1, were lowly expressed in ovarian cancer cells." (PMID 37124501, 2023). "RT-qPCR analysis revealed that URI1, PAK2, PARP1, CLU, and TIMP3 were significantly upregulated, while UBB, RPL11, CAV1, NUPR1, and Hsp90ab1 were significantly downregulated in the ovarian cancer samples." (PMID 37124501, 2023). "Therefore, clusterin could be a potential molecular for ovarian cancer treatment." (PMID 26293319, 2015). "Either siRNA or second generation antisense oligodeoxynucleotide against CLU (OGX-011), which is currently evaluated in clinical phase II trials in other cancer s, was used to modulate sensitivity to paclitaxel (TX) in ovarian cancer cells in vitro." (PMID 22185350, 2011). "For ovarian cancer, the tags CAACTAATTC and TGTGGGAAAT belong to the clusterin (CLU) and secretory leukocyte peptidase inhibitor (SLPI) genes, respectively." (PMID 21179408, 2010). "The expression of CPL, CLU, ACT and AAT was determined for 17 biopsy samples of patients with ovarian carcinoma." (PMID 18637207, 2008).
ovarian carcinoma (continued). "Furthermore, using a Human Apoptosis Array Kit consisting of 35 apoptosis-related proteins (R&D) with either miR-141-overexpressing or KLF12 knockdown ovarian cancer cells, 8 out of 35 proteins (HO-2/HMOX2, ph-Rad 17, CIAP-2, survivin, HSP-70, TNFR1/TNFRSF1A, clusterin and XIAP) were upregulated." (PMID 28095864, 2017). "Although our observations were consistent with previously reported ones that s-CLU mediates cisplatin-induced resistance in ovarian cancer, CLU expression was found not to be a prognostic factor among patients with advanced-stage (stage III/IV) ovarian cancer in our patient cohort (data not shown)." (PMID 22185350, 2011). "According to the findings of the CPTAC project, total CLU protein expression was lower in primary tissues of BC, HNSC, CC, UCEC, LUAD, and ovarian cancer (p < 0.001) than in non-tumor tissues." (PMID 36685863, 2022). "The purpose of this study was to investigate whether clusterin (CLU), an antiapoptotic molecule, could be a potential predictor molecule for ovarian cancer and whether or not targeting this molecule can improve survival of ovarian cancer patients." (PMID 22185350, 2011).
myocardial infarction (25 papers, 2009 to 2025). Gross necrosis of the myocardium, as a result of interruption of the blood supply to the area, as in coronary thrombosis. "In vivo, CLU−/− mice were more susceptible to acute myocardial infarction than CLU+/+ mice." (PMID 40418078, 2025). "The roles of clusterin in myocardial infarction, myocarditis, and vascular injury have been extensively studied." (PMID 40671119, 2025). "Third, we investigated clusterin dynamics only during a brief period after myocardial infarction; long term dynamics and a possible prognostic factor for mortality should be the subject of additional studies." (PMID 32605184, 2020). "Serum clusterin levels were reported to increase in various conditions such as myocardial infarction, inflammation, apoptosis, and oxidative stress." (PMID 33256720, 2020). "Existence of single cardiomyocytes positive for clusterin after acute myocardial infarction (AMI) suggests a role for clusterin in the protection of cardiomyocytes." (PMID 31534454, 2019). "Intravenous clusterin administration after myocardial infarction in rat has been demonstrated to reduce infarct size and improved survival." (PMID 26962868, 2016). "CLU, or Apo J, has been suggested to play a compensatory protective role by acting as an inflammatory modulator in myocardial infarction." (PMID 26061039, 2015). "The serum levels of some protein biomarkers like clusterin and apolipoprotein J were elevated significantly in type 2 DM and during development of coronary heart disease or at myocardial infarction." (PMID 26273663, 2015). "An elevated serum clusterin level was observed in patients with coronary artery disease and myocardial infarction." (PMID 22792249, 2012). "Both an increase and decrease of clusterin in acute myocardial infarction (AMI) has been reported." (PMID 32605184, 2020). "Moreover, significant changes in clusterin gene level have been detected in patients with acute myocardial infarction (AMI) and increased levels of selectin L (SELL) are associated with ischemic stroke." (PMID 29530068, 2018). "In addition, previous studies have also shown that clusterin mRNA and protein concentrations are upregulated in models of myocarditis and ischemia and localized in necrotic areas of cardiomyocytes after myocardial infarction." (PMID 23956692, 2013). "Blood clusterin levels have been shown to change in different disease states including numerous cancers and systemic lupus erythematosus as well as in diabetic type II patients and in patients with developing coronary heart disease, or myocardial infarction." (PMID 19348683, 2009). "Inflammation could represent a key mechanistic link between clusterin and myocardial infarction." (PMID 40418078, 2025). "Second, while the effects of clusterin overexpression on human cardiovascular disease are unclear and may be pro-atherosclerotic or protective, clusterin serum levels correlate with severity of coronary artery stenosis and are highest during active myocardial infarction." (PMID 26986213, 2016). "We recently identified clusterin (CLU) as a biomarker of cardiac remodelling and HF after myocardial infarction." (PMID 39671261, 2024). "It has been suggested that the effect of clusterin on myocardial infarction is independent of clustein binding with its receptor, megalin." (PMID 26962868, 2016).
neuroblastoma (22 papers, 2011 to 2025). Neuroblastoma (NB) is the most common solid, extracranial childhood tumor. "The expression of clusterin, also known as apolipoprotein J is known to be induced by processes such as oxidative stress, as well as apoptotic stimuli and this protein has also been implicated in inhibition of neuroblastoma cell invasion." (PMID 21365000, 2011). "Mice with a disrupted CLU gene are more susceptible to developing neuroblastomas when MYCN is transgenically expressed, suggesting that the MYCN-CLU axis is crucial and that CLU acts as a repressor in tumorigenesis." (PMID 39253532, 2024). "In tumors with amplified MYCN, CLU is strongly downregulated, in part through transcriptional induction of miR-17-92, and it was demonstrated that mice with deregulated CLU are more prone to the formation of neuroblastomas." (PMID 37685987, 2023). "In neuroblastoma cells, CLU expression is repressed by the TF MYCN through the recruitment of HDACs and Polycomb group proteins." (PMID 37685987, 2023). "Neuronal MYC (MYCN), a member of the MYC family, has been identified as a CLU negative regulator in human neuroblastoma cells." (PMID 37685987, 2023). "Loss of H3K27 methylation upregulates CLU and NGFR, induces apoptosis, and potentiates resveratrol-induced cell death in neuroblastoma cells." (PMID 37345170, 2023). "Neuroblastoma cells treated with a sub‐lethal level of iron exhibit increased clusterin protein and expression levels." (PMID 35984750, 2022). "In vitro studies using neuroblastoma cells incubated with TTR oligomers revealed intracellular clusterin overexpression and increased levels of clusterin secreted to the culture medium." (PMID 33362465, 2020). "Time-dependent increases in CLU mRNA and protein are also observed in neuroblastoma cells under conditions of lipid peroxidation and production of ROS, suggested to be a protective mechanism inhibiting cellular damage during oxidative stress." (PMID 30872998, 2019). "CDKN1A/p21 is one of the major proteins involved in negative regulation of progression through the cell cycle while CLU is a multifunctional protein proposed to function as a tumor suppressor in Neuroblastoma." (PMID 26062444, 2015). "For instance, CLU has been identified as a tumor suppressor in neuroblastomas." (PMID 40606578, 2025). "Early research has indicated that overexpression of α-synuclein in SH-SY5Y human neuroblastoma cells increases clusterin expression, whereas decreasing clusterin expression aggravates α-synuclein deposition, highlighting the role of clusterin in modulating α-synuclein accumulation." (PMID 39049102, 2024). "HSPA5, HERPUD1, and CLU expression increased in vivo and cultured neuroblastoma cells." (PMID 35984750, 2022). "Interestingly, the epigenetically silenced neuroblastoma tumor suppressor gene CLU was induced in both cell lines, together with another tumor suppressor CASZ1 only in IMR32 cells." (PMID 32210188, 2020). "In order to determine whether the expression profiles of human and rodent brain CLU proteins are comparable, human CLU constructs were overexpressed in a human neuroblastoma cell line (SH-SY5Y cells) and analyzed as indicated in the section above." (PMID 31738162, 2019). "It has been shown in neuroblastoma cells, that cell survival is promoted by the pro-proliferative and pro-survival activity of HSP60 by forming a physical association with and inhibition of the intracellular protein clusterin (also known as Apolipoprotein J, TRPM-2 and SGP-2)." (PMID 28914774, 2017). "MiR-137 targets the EZH2 3′UTR in neuroblastoma cells, leading to decreased H3K27 methylation in the genomic regions of tumor suppressor genes clusterin (CLU) and nerve growth factor receptor (NGFR)." (PMID 37345170, 2023). "EZH2 has been independently shown to repress tumor suppressor genes in neuroblastoma, including CASZ1, RUNX3, NGFR, and CLU." (PMID 32537432, 2020).
neuroblastoma (continued). "A recent study using N2a mouse neuroblastoma cultures and in vivo Drosophila models of ALS showed that CLU overexpression reduces TDP-43 protein aggregation and toxicity." (PMID 30872998, 2019). "In neuroblastoma, MYBL2 directly regulates expression of ApolipoproteinJ/Clusterin and thereby mediates resistance to apoptosis induced by doxorubicin." (PMID 28640249, 2017). "Moreover, LSD1 co-localizes with N-MYC at the promoter of CDKN1A (p21CIP) and Clusterin (CLU), two tumor suppressor genes, thereby functionally cooperating with N-MYC in neuroblastoma initiation and progression." (PMID 28505071, 2017).
colon carcinoma (21 papers, 2006 to 2025). "One final leader gene for colon cancer, CLU, was identified from the cytoplasm, endoplasmic reticulum, Golgi apparatus-specific networks, and the disease network." (PMID 36226184, 2022). "A previous study has found that the high mRNA expression level of CLU in colon cancer patients indicated a poor prognostic outcome." (PMID 36226184, 2022). "In other cell systems, p38 MAPK mediates MMP-9 upregulation in response to several stimuli, including TNF-α and SDF-1/CXCR7 in bladder and ovarian, respectively, carcinoma cells, and clusterin/thrombospondin-1 in platelet-stimulated colon cancer." (PMID 27829220, 2016). "In colon carcinoma, clusterin has been used as a novel prognostic and predictive marker which is observed in aggressive tumors and metastatic nodules." (PMID 26293319, 2015). "In human colon cancer, the expression of CLU is considered to be a marker for tumor development and is associated with poor outcome and decreased disease-free survival." (PMID 26399194, 2015). "CLU codifies the protein Clusterin that has been described as both tumor suppressor and pro-survival factor in colon cancer depending on the intra- and extracellular microenvironment crosstalk." (PMID 24597571, 2014). "Here, we demonstrate that abrogation of the Wnt signaling pathway in colon carcinoma cells lead to up-regulation of CLU." (PMID 17634137, 2007). "Clusterin (CLU) plays a key role in the cell transformation process and has been reported to be overexpressed in several human tumor tissues, such as prostate, breast, renal, ovarian, and colon cancer." (PMID 33807999, 2021). "Similarly, CLU has been proposed to be a new potential prognostic and predictive marker for colon carcinoma aggressiveness, since overexpression of CLU is observed in highly aggressive tumors as well as metastatic nodules." (PMID 22185350, 2011). "To determine if Clusterin protein levels are affected by alterations in Wnt signaling activity, we transiently transfected the colon carcinoma cell lines, LS174T and HCT116, with a fusion construct consisting of GFP fused to the cytoplasmic domain of E-cadherin." (PMID 17634137, 2007). "The pro-survival protein clusterin (CLU) plays an important role in promoting tumor cells proliferation and serves as a marker for colon cancer." (PMID 22545109, 2012).
pancreatic cancer (21 papers, 2011 to 2025). "A recent study on the molecular mechanism of BRCA mutations and CAF in pancreatic cancer reported enhancement of clusterin in BRCA1 or BRCA2 mutant CAF in a heat shock factor 1-dependent manner." (PMID 38182557, 2024). "Here the authors show that loss of BRCA function in pancreatic cancer cells leads to HSF1–dependent accumulation of immune-regulatory clusterin-positive cancer associated fibroblasts." (PMID 36316305, 2022). "Nevertheless, the strong association between clusterin expression and lymph node metastasis suggests that clusterin can be used as an adjunct to lymph node positivity to predict survival in pancreatic cancer." (PMID 22799602, 2012). "In contrast, the knockdown of CLU in pancreatic cancer cells limited tumor progression by inhibiting the NF-κB signaling pathway." (PMID 39627493, 2025). "In support of these findings, knockdown of CLU has been found to be critical for gemcitabine-induced apoptosis in human pancreatic cancer cells, which involves downregulation of NF-κB and Bcl-2." (PMID 39253532, 2024). "In summary, the study indicates that the HNF1B/CLU pathway serves to hinder the advancement of pancreatic cancer." (PMID 37685987, 2023). "In pancreatic cancer, the inhibition of CLU decreases NF-κB/bcl-2 pathway activity, thereby increasing the apoptotic effect of gemcitabine chemotherapy." (PMID 37685987, 2023). "In vitro studies revealed that clusterin is involved in acquired gemcitabine resistance in BCa cells and pancreatic cancer cells by increasing Akt phosphorylation and cell survival." (PMID 36292976, 2022). "Another recent report demonstrated that inhibition of clusterin-dependent ERK1/2 activation sensitized pancreatic cancer cells to gemcitabine treatment." (PMID 24705102, 2013). "Clusterin was silenced by serial concentration of OGX-011 transfection in pancreatic cancer MIAPaCa-2 and BxPC-3 cell lines, then treated with serial concentration of gemcitabine." (PMID 22967941, 2012). "Knockdown of clusterin by OGX-011 transfection sensitizes pancreatic cancer cells to gemcitabine by inhibition of gemcitabine -induced clusterin-pERK1/2 activation." (PMID 22967941, 2012). "A highly significant clusterin protein immunoreactivity was shown in pancreatic cancer cells(P < 0.05)." (PMID 21609464, 2011). "Pancreatic cancer tissues expressed significantly higher levels of clusterin than did normal pancreatic tissues (P < 0.01)." (PMID 21609464, 2011). "Immunohistochemistry for clusterin was performed on 50 primary pancreatic cancer tissues and 25 matched backgrounds, and clusterin expression in 5 pancreatic cancer cell lines was quantified by Western blot and PT-PCR." (PMID 21609464, 2011). "Clusterin protein immunoreactivity was detected both in matched backgrounds and pancreatic cancer cells." (PMID 21609464, 2011). "To extend these observations to pancreatic cancer, we measured clusterin expression levels in pancreatic cancer tissue samples and cell lines and sought to determine the role of clusterin in conferring gmcitabine resistance in pancreatic cancer cells." (PMID 21609464, 2011). "The association between clusterin protein expression and gmcitabine IC50 was examined in five pancreatic cancer lines:PT45-P1, T3M4, BxPc-3, Capan-1 and PancTu-1." (PMID 21609464, 2011). "Clusterin expression levels were correlated with gmcitabine resistance in pancreatic cancer cell lines, and OGX-011 significantly decreased BxPc-3 cells resistance to gmcitabine (P < 0.01)." (PMID 21609464, 2011). "We also shown in our study that clusterin expression is significantly higher in pancreatic cancer tissues than in normal pancreatic tissue." (PMID 21609464, 2011). "The silencing of CLU has been demonstrated to induce senescence in pancreatic cancer cells." (PMID 40573993, 2025). "In addition, the extracellular chaperone Clusterin (CLU) has been shown to be a mediator of chemoresistance in pancreatic cancer." (PMID 37835519, 2023).